CCL14 (C-C motif chemokine ligand 14)
Description:
Has weak activities on human monocytes and acts via receptors that also recognize MIP-1 alpha. It induces intracellular Ca(2+) changes and enzyme release, but no chemotaxis, at concentrations of 100-1,000 nM, and is inactive on T-lymphocytes, neutrophils, and eosinophil leukocytes. Enhances the proliferation of CD34 myeloid progenitor cells. The processed form HCC-1(9-74) is a chemotactic factor that attracts monocytes, eosinophils, and T-cells and is a ligand for CCR1, CCR3 and CCR5.
Synonyms: HCC-1/HCC-3; NCC2; SCYA14; HCC-1; HCC-3; NCC-2; SCYL2; CKb1; MCIF; CC-1; CC-3; HCC-1(1-74); SY14
Tractability: Antibody: UniProt places it where antibodies can reach, with medium confidence; UniProt predicts a signal peptide or a membrane-spanning region; its Gene Ontology location is reachable by antibodies, with medium confidence.
Gene: Protein-coding gene on chromosome 17 (35,983,288 to 35,987,033, reverse strand). Ensembl gene ENSG00000276409.
Subcellular location: Secreted
Gene Ontology:
Molecular function: CCR chemokine receptor binding; chemokine activity
Biological process: antimicrobial humoral immune response mediated by antimicrobial peptide; cell chemotaxis; chemokine-mediated signaling pathway; inflammatory response; intracellular calcium ion homeostasis; positive regulation of cell migration; positive regulation of cell population proliferation; immune response
Cellular component: extracellular region
Genetic constraint (gnomAD): Loss-of-function variants: 4 observed, 5.23 expected, observed/expected ratio (o/e) 0.77, 90% interval 0.37 to 1.64. That is too few expected variants to judge how well the gene tolerates losing a copy. Missense variants: 117 observed, 116.39 expected, observed/expected ratio (o/e) 1.01, 90% interval 0.86 to 1.17. Synonymous variants: 49 observed, 44.54 expected, observed/expected ratio (o/e) 1.1, 90% interval 0.87 to 1.4.
Homologues: Orthologues: chimpanzee CCL14 (97% identical), macaque CCL14 (85% identical), dog CCL14 (67% identical), rabbit CCL14 (66% identical), pig CCL14 (60% identical), guinea pig CCL14 (58% identical), zebrafish ccl35.1 (30% identical), zebrafish ccl35.2 (30% identical). Paralogues in human: CCL23 (44% identical), CCL3 (44% identical), CCL3L3 (44% identical), CCL4 (43% identical), CCL18 (41% identical), CCL16 (40% identical), CCL4L2 (40% identical), CCL15 (39% identical), CCL26 (37% identical), CCL5 (37% identical), CCL7 (32% identical), CCL8 (32% identical), and 14 more.
Diseases named in the same sentence as CCL14 in open-access papers:
CCL14 is named in the same sentence as 55 diseases in open-access papers, as found by Europe PMC text mining. Sharing a sentence is not in itself a finding about the gene and the disease. The quoted sentences say what the papers report.
hepatocellular carcinoma (13 papers, 2019 to 2024). A malignant tumor that arises from hepatocytes. "High CCL14 expression is linked to long-term outcome in epithelial ovarian cancer patients and inferior prognosis in hepatocellular carcinoma." (PMID 38887558, 2024). "CCL14 reduces the activation of the Wnt/β-catenin pathway in hepatocellular carcinoma cells, which inhibits their proliferation and causes their apoptosis." (PMID 33182504, 2020). "Although CCL14 was reported to play a role in breast cancer and hepatocellular carcinoma progression as a prognostic biomarker, CCL14 expression in the TME of gastric cancer is not fully known." (PMID 38887558, 2024). "C-C Motif Chemokine Ligand 14 (CCL14) attenuates hepatocellular carcinoma (HCC) cell proliferation and promotes apoptosis through the Wnt/β-catenin signaling pathway." (PMID 37895310, 2023). "It was reported that the overexpressed CCL14 suppressed proliferation and promoted apoptosis of hepatocellular carcinoma cells via inhibition of the activation of the Wnt/β‐catenin pathway." (PMID 36054420, 2022). "Correlation of CCL14 mRNA expression and prognosis in hepatocellular carcinoma with different clinicopathological factors by Kaplan-Meier plotter." (PMID 31927532, 2020). "As per studies, CXCL16 could help to locally sustain the cytotoxic T lymphocyte (CTL) response for effective tumor control and the overexpression of CCL14 could inhibit the proliferation of hepatoma cells and promote apoptosis." (PMID 37711200, 2023). "CCL14 is a member of CC chemokines and its role in hepatocellular carcinoma (HCC) is still unknown." (PMID 31641099, 2019). "Moreover, CCL14 attenuated the proliferation of hepatocellular carcinoma (HCC) cells by inhibiting the cell-cycle progression and promoting apoptosis, and it suppressed the growth via the Wnt/β-catenin signaling." (PMID 35377900, 2022). "Moreover, CCL14 attenuates hepatocellular carcinoma (HCC) cell proliferation by inhibiting cell cycle progression and promoting apoptosis in vitro and suppresses HCC growth in vivo via the Wnt/β-catenin signalling pathway." (PMID 31991604, 2020). "Our results are not the same as that of other studies of CCL14 expression in hepatocellular carcinoma and epithelial ovarian cancer." (PMID 38887558, 2024). "However, the relationship between CCL14 expression, tumor immunity, and prognosis in Hepatocellular Carcinoma (HCC) remain unclear." (PMID 31927532, 2020).
acute kidney injury (9 papers, 2021 to 2025). Sudden and sustained deterioration of the kidney function characterized by decreased glomerular filtration rate, increased serum creatinine or oliguria. "Urinary Chemokine (C–C motif) ligand 14 (CCL14) is a biomarker associated with persistent severe acute kidney injury (AKI)." (PMID 38666354, 2024). "Urinary C–C motif chemokine ligand 14 (CCL14) has been described as an effective marker for delayed recovery of acute kidney injury (AKI), yet its efficacy has been found to vary between different trials." (PMID 37596698, 2023). "CO-88 Urinary CCL14 biomarker to predict renal replacement therapy initiation in critically ill patients with severe acute kidney injury?" (PMID 35729416, 2022). "The performance of renal resistance index (RRI) in predicting persistent sepsis-associated acute kidney injury (S-AKI) remains debatable, and the value of urinary C–C motif chemokine ligand 14 (CCL14) in predicting persistent S-AKI has not been validated yet." (PMID 36797554, 2023). "Another study reported that urinary C-C motif chemokine ligand 14 (CCL14), a newly discovered biomarker for persistent acute kidney injury (AKI), may help improve the clinical management of AKI patients." (PMID 39081365, 2024).
breast carcinoma (8 papers, 2015 to 2025). "JARID1B in MCF-7 and MDA-MB-231 of breast cancer cells inhibited cell angiogenesis and invasion by suppressing CCL14 expression." (PMID 33592583, 2021). "However, JARID1B can act in concert with LSD1, to remove three H3K4 methylation marks from the C-C Motif Chemokine Ligand 14 (CCL14) promoter, resulting in inhibition of chemokine-mediated migration, angiogenesis and breast cancer metastasis." (PMID 33803458, 2021). "However, other studies had shown that the CCL14 chemokine signaling pathway promotes cancer progression, and inhibiting the expression of CCL14 could reduce the ability of breast cancer to metastasize." (PMID 38075694, 2023). "Low CCL14 mRNA levels correlate with a worse prognosis in several cancers, including HCC, breast cancer, lung cancer, and pancreatic ductal adenocarcinoma." (PMID 31927532, 2020).
gastric cancer (7 papers, 2020 to 2024). A primary or metastatic malignant neoplasm involving the stomach. "Second, the relationship between cancer-associated CCL14 expression and the TILs remains to be determined in order to find evidence that CCL14 and immune cells jointly exert anti-tumor function in gastric cancer cells." (PMID 38887558, 2024). "Both the GEO database and IHC in the TMA showed that CCL14 expression was significantly elevated in gastric cancer cells and was associated with an inferior prognosis." (PMID 38887558, 2024). "The conclusions demonstrated that the higher expression of CCL14 in gastric cancer cells was associated with a poor prognosis (p = 0.008)." (PMID 38887558, 2024). "Our study illustrated that CCL14 is a poor prognosis biomarker in gastric cancer, which may be associated with the potential for immunotherapy." (PMID 38887558, 2024). "The outcome of gastric cancer patients with high CCL14 expression in gastric cancer cells, high preoperative CA199 levels, and an advanced TNM stage had significantly dismal survival." (PMID 38887558, 2024). "Fortunately, the cutoff point of CCL14 protein expression in stomach cancer cells or TILs was 50 according to the outcome of these gastric cancer patients using X-tile software." (PMID 38887558, 2024). "We found that the CCL14 protein was separately expressed in the carcinoma cells and TILs in stomach cancer tissues." (PMID 38887558, 2024). "First, we analyzed CCL14 expression in the TME of gastric cancer tissue, and our results lack cross-talk clues between the tumor cells and TILs." (PMID 38887558, 2024). "CCL14 mRNA expression was significantly higher in gastric cancer tissue compared to benign stomach tissue using data downloaded from the GEO database, which included 300 gastric cancer samples and 100 non-malignant samples." (PMID 38887558, 2024). "In the current study, we performed CCL14 representation and studied its interrelation with gastric cancer prognosis." (PMID 38887558, 2024). "This study investigated the expression of chemokine CCL14 and its relationship with TILs in gastric cancer cells through the bioinformatics analysis method and high-dimensional IHC staining with multispectral image analysis." (PMID 38887558, 2024). "We ascertained statistically significant lower expression of the CCL14 protein in gastric cancer cells than in gastric mucosal epithelial cells (79.43 ± 54.80 vs. 100.75 ± 48.17, p = 0.008)." (PMID 38887558, 2024). "Kaplan–Meier survival and multivariate analyses showed that the CCL14 expression in gastric cancer cells was an independent prognostic factor." (PMID 38887558, 2024). "This investigation also indicated that CCL14 expression in gastric cancer cells was relevant to differentiation types and the tumor status." (PMID 38887558, 2024). "In this study, using the bioinformatics system and TMA-mIHC, we proved that CCL14 is a prospective biomarker of gastric cancer." (PMID 38887558, 2024). "Correlation between the expression of CCL14 and tumor-infiltrating immune cells (TILs) and the pathological characteristics of patients with gastric cancer." (PMID 38887558, 2024). "The survival plots also indicated that gastric cancer patients with a high expression of CCL14 in gastric cancer cells had a significantly shorter survival time." (PMID 38887558, 2024). "It is possible that CCL14 regulates the migration of TILs into gastric cancer tissues and affects the clinical outcome." (PMID 38887558, 2024). "CCL14 protein expression, TILs, and immune checkpoints were detected by multiple immunohistochemistry analyses in gastric cancer tissue microarrays." (PMID 38887558, 2024). "Because the role of the same gene or protein is not the same in different cancer types, we first investigated CCL14 protein expression in the gastric cancer TME and found that CCL14 is an outcome factor in gastric cancer." (PMID 38887558, 2024).
gastric cancer (continued). "CCL14-positive staining was preponderantly localized in gastric cancer cells, gastric mucosal epithelial cells, TILs, and immune cells in the gastric mucosa, which was found using imaging software." (PMID 38887558, 2024). "We assessed CCL14 mRNA expression and its interrelation with tumor-infiltrating immune cells (TILs) using bioinformatics analysis in gastric cancer." (PMID 38887558, 2024). "This investigation explored the CCL14 expression in stomach cancer and its relation with the clinical outcome." (PMID 38887558, 2024). "It is clear that CCL14 protein expression in gastric cancer cells is interrelated to differentiation (p = 0.026) and tumor depth (p = 0.034)." (PMID 38887558, 2024). "Our results demonstrated that CCL14 is a prospective therapeutic for gastric cancer." (PMID 38887558, 2024). "Therefore, we demonstrated the relationship of mRNA expression between CCL14 and TILs in gastric cancer tissues." (PMID 38887558, 2024). "Some types of TILs in the TME of gastric cancer were correlated with CCL14 expression." (PMID 38887558, 2024). "In addition, the CCL14 protein in the TILs of gastric cancer tissues was related to Lauren’s type cells, T cells (CD4+ and CD8+), and CD68+ macrophages in the TME." (PMID 38887558, 2024). "We also characterized the prognostic value of CCL14 mRNA expression for gastric cancer." (PMID 38887558, 2024). "Finally, it is unclear whether CCL14 would also induce immune escape in in vivo gastric cancer models." (PMID 38887558, 2024). "We used immunohistochemical analysis to investigate the expression of the CCL14 protein and other immune-related markers in TMA sections containing 133 gastric cancer tissues and 67 benign gastric mucosa tissues." (PMID 38887558, 2024). "The CCL14 protein was related to tumor differentiation and tumor depth and positively correlated with the presentation of LAG3 and PD-L1 in gastric cancer cells." (PMID 38887558, 2024). "In patients with stomach cancers, GPX3, CLEC3B, CFD, GSN, and CCL14 were the leading five genes that were most significantly downregulated." (PMID 33828156, 2021). "Co-expression network analysis of datasets from the GEO database has identified four key genes involved in gastric cancer progression including ITGAX, chemokine (C-C motif) ligand 14 (CCL14), alcohol dehydrogenase iron-containing protein 1 (ADHFE1), and Homeobox B13 (HOXB13)." (PMID 39845786, 2024). "Furthermore, the statistics results indicated no relation between CCL14 expression in cancer cells and TILs in gastric cancer tissues (r = 0.569, p = 0.133) via Pearson’s correlation." (PMID 38887558, 2024).
Sepsis (5 papers, 2021 to 2025). Sepsis is defined as life-threatening organ dysfunction caused by a dysregulated host response to infection. "The model uses routine clinical data to predict persistent SA-AKI in patients with sepsis in the ICU environment quite well, and its diagnostic performance is even superior to that of CCL14, a biomarker known for diagnosing persistent SA-AKI." (PMID 40200699, 2025). "If the discovery of CCL14 as a predictor of persistent AKI is not the first one to suggest the role of monocytes/macrophages in the pathophysiology of AKI, especially in sepsis, it offers the opportunity to identify new approaches of AKI therapy." (PMID 33856581, 2021). "Univariate logistic regression analysis demonstrated significant associations between renal non-recovery and several factors, including age, sepsis severity, serum lactate level, SCr at enrollment, AKI stage, as well as urinary levels of [TIMP-2]•[IGFBP7] and CCL14 (all with P < 0.05)." (PMID 38702662, 2024).
co-infection (3 papers, 2016 to 2024). "Co-infection of monocytes with PRRSV-2 strain IAF-Klop and S. suis led to synergistic effects on the expressions of IL-6, CCL5, and TNF-α, and additive effects on productions of CCL4, CCL14, CCL20, IL-15, and PTGS2 (COX-2)." (PMID 38547254, 2024).
colon cancer (3 papers, 2016 to 2023). "Tumor progression-enhancing effects of CXCL7 and CXCL5 on CCA cells were described, in contrast, it has also been reported that CCL14 inhibited the proliferation and invasion of colon cancer cells." (PMID 35377900, 2022). "Macrophage infiltration appears to be related to CXCL12–CXCR4 in thyroid, head and neck, stomach, and colon cancers and to CCL14,CCL23–CCR1 in lung cancers." (PMID 27549193, 2016).
COVID-19 (3 papers, 2020 to 2025). A disease caused by infection with severe acute respiratory syndrome coronavirus 2. "In contrast, pro-inflammatory cytokines and chemokines, including CCL14, CCL23, IL7, IL16 and IL18, were preferentially expressed in men, underlying the higher susceptibility of men developing cytokine release syndrome in COVID-19." (PMID 32974111, 2020). "Multiple studies show high levels of proinflammatory cytokines such as IL-1, TNF, IFNs, IL-6, IL-8, IL-18, IL-17α, G-CSF, and GM-CSF, as well as chemokines, such as MCP-1, IP-10, MIP-1α, CXCL10, CCL2, CCL4, CCL14, CCL19, and CCL25 in severe cases of COVID-19." (PMID 40076291, 2025).
lung carcinoma (3 papers, 2016 to 2023). "Interestingly, CCL14 was a risk factor in lung cancer and colorectal cancer and a protective factor in small intestine tumors." (PMID 38075694, 2023). "Cochrane’s Q test did not provide evidence of heterogeneity between CCL14 (p = 0.916), CCL19 (p = 0.446), CCL20 (p = 0.130), CCL21 (p = 0.878), CCL27 (p = 0.762), CXCL9 (p = 0.340) and CXCL13 (p = 0.770) and lung cancer." (PMID 38075694, 2023).
ovarian carcinoma (3 papers, 2020 to 2023). A malignant neoplasm originating from the surface ovarian epithelium. "Moreover, the upregulation of CCL14 was associated with a more favorable prognosis in ovarian cancer patients." (PMID 37175004, 2023). "Another study on epithelial ovarian cancer revealed that CCL14 upregulation is associated with a favorable prognosis.The differentially expressed immune-associated genes may play important roles in the development of tumor." (PMID 34424809, 2021).
stomach cancer (3 papers, 2021 to 2024). "Here, we aim to discover the connection between chemokine ligand 14 (CCL14) expression in the gastric tumor microenvironment (TME) and its clinical significance and investigate its correlation with immune cell infiltration." (PMID 38887558, 2024).
colorectal cancer (2 papers, 2023 to 2024). A primary or metastatic malignant neoplasm that affects the colon or rectum. "In colorectal cancer, CCL14 was a risk factor, while in small intestine tumors it was a protective factor." (PMID 38075694, 2023).
liver cancer (2 papers, 2022 to 2023). An epithelial or non-epithelial malignant neoplasm that arises from the liver. "The results showed that the expression of PAIP1 had a significant negative correlation (P < 0.05) with that of APOC3, CCL14, IL1RN, SERPINA3, and HAMP in liver cancer tissues." (PMID 37101794, 2023).
liver cirrhosis (2 papers, 2019 to 2025). "The predictive value of CCL14 were also observed in high differentiation (P = 0.026), liver cirrhosis (P = 0.003) and no tumor capsule (P = 0.024) subgroups." (PMID 31641099, 2019). "CCL14 also displayed its predictive value in high differentiation (P = 0.026), liver cirrhosis (P = 0.003), and no tumor capsule (P = 0.024) subgroups." (PMID 31641099, 2019).
angiomyolipoma (1 paper, 2026). A neoplasm with perivascular epithelioid cell differentiation often associated with tuberous sclerosis. "Subgroup analyses demonstrated higher CCL14 levels in patients with angiomyolipomas (AMLs) versus those without, and in CT grade III versus grade I/II." (PMID 41559739, 2026).
asthma (1 paper, 2024). "Our research also linked high levels of CCL14 expression to actions that can aggravate asthma." (PMID 39030403, 2024). "Additionally, GSEA demonstrated that increased CCL14 levels were mostly associated with pathways related to asthma, the CTLA4 pathway, the intestinal immune network for IgA formation, CAMs, and the PD-1 signaling pathway." (PMID 39030403, 2024). "Numerous pathways, including those involved in asthma, the CTLA4 pathway, the intestinal immunological network for IgA production, CAMs, and the programmed death 1 (PD-1) signaling pathway, have been associated with elevated levels of CCL14." (PMID 39030403, 2024).
bladder cancer (1 paper, 2021). "The role of CCL14 in tumor progression is unclear and underreported, especially in bladder cancer." (PMID 33894748, 2021).
brain tumor (1 paper, 2024). "Our results showed that CCL14 expression was greater in brain tumor, esophageal cancer, and lymphoma tissues than in normal tissue samples." (PMID 39030403, 2024).